GSDMD (gasdermin D)
Diseases named in the same sentence as GSDMD in open-access papers (continued):
Sharing a sentence is not in itself a finding about the gene and the disease.
cancer (continued). "Strong evidence has demonstrated that the pyroptosis process is highly involved in the pathogenesis and progression of cancer by inducing GSDMD-dependent caspase-1 inflammasome pathways and other GSDM-dependent non-inflammasome signaling cascades." (PMID 36003332, 2022). "Another DNA methyltransferase inhibitor, γ-oryzanol, upregulates the expression of GSDMD in cancer cells, thus enhancing cancer immunotherapy in animal models." (PMID 35856558, 2022). "For example, certain drugs or molecules (metformin, anthocyanin, DHA(Docosahexaenoic Acid), 2-(naphthoyl) ethyl trimethylammonium iodide) can promote pyroptosis of cancer cells by activating GSDMD." (PMID 35883480, 2022). "Our pan-cancer analysis indicates that the expression of GSDM genes (in particular GSDMB, GSDMC, and GSDMD) was significantly associated with the survival of patients with certain types of urinary tract system cancer." (PMID 36003332, 2022). "In triple-negative breast cancer (TNBC), docosahexaenoic acid (DHA, an omega-3 fatty acid) induces caspase-1 activation, which leads to GSDMD division, secretion of IL-1β, and membrane pore formation, thus promoting cancer cell death." (PMID 35359956, 2022). "GSDMD-enh3 exhibits relatively high binding peaks in a variety of cancer cell lines, indicating that targeting the GSDMD-enh3 is more likely to be applicable for a variety of cancers." (PMID 35008400, 2022). "Consistently, we observed a highly evident GSDMD translocation to the membrane of CXCR4+ SW1417 cells with very high intensity in 10–20% of exposed cancer cells, mainly after 48 hours of exposure to T22-PE24-H6." (PMID 35532120, 2022). "There are high binding peaks around the GSDMD-enh3 on the ChIP-Seq data in various cancer cell lines (HepG2, GM12878, PANC-1, and A549), indicating that there are potential enhancers upstream of GSDMD." (PMID 35008400, 2022). "The concomitant effects of IL-18, IL-1β and NLRP3 elevation were ignored in studies claiming that GSDMD mediates pyroptosis in cancer cells." (PMID 36091247, 2022). "This is consistent with published reports that ROS induced GSDMD cleavage and pyroptosis in cancer cells." (PMID 36473850, 2022). "Compared to the other gasdermin family genes, GSDMD had a higher average expression within all cancer types." (PMID 35922531, 2022). "The results showed that dietary polyphenols induced pyroptosis in cancer cells mainly through the GSDMD and GSDME pathways." (PMID 36091247, 2022). "Increasing studies suggested that elevated GSDMD expression was important for cancer invasion, metastasis, and prognosis." (PMID 35102195, 2022). "A study found that GSDMD deficiency reduces the cytolytic capacity of CD8+ T cells, and GSDMD is required for an optimal cytotoxic T lymphocytes response in cancer cells." (PMID 36505798, 2022). "Since the advent of the protein known as gasdermin D (GSDMD), which is engaged in the pyroptotic process in 2015, abundant treatments have been developed to trigger pyroptosis for cancer." (PMID 36119049, 2022). "These functions and mechanisms recently had been reported to relate with cancer therapy, especially the GSDMD and GSDME." (PMID 34421915, 2021). "GSDMD serves as a double-edged sword in tumorigenesis: on the one hand, it can trigger pyroptosis to facilitate cancer cell death; on the other hand, it can also result in poor prognosis in some cases." (PMID 34522213, 2021). "GSDMD has intensively been investigated in microbial infection and cancer since GSDMD was identified as the main executioner of pyroptosis in 2015." (PMID 34899666, 2021). "Overall, despite its uncertain role in tumorigenesis, GSDMD-mediated pyroptosis in cancer has attracted huge interest from researchers worldwide and has remained a critical study topic, indicating its importance as a new therapeutic target." (PMID 34298833, 2021).
cancer (continued). "NLRP3 inflammasome activation, caspase-1 activation, release of IL-1β and IL-18 pro-inflammatory cytokines and gasdermin D-mediated pyroptotic cell death are important mechanisms involved in inflammation-induced cancer." (PMID 34452150, 2021). "GSDMD, which was extensively investigated in various cancers, was involved in the unfavorable pyroptosis gene set in this study." (PMID 35198000, 2021). "Although GSDMD represents a double-edged sword in cancer progression, the activation of GSDMD is promising in cancer suppression." (PMID 34522213, 2021). "Mechanistic studies have revealed that DHA can inhibit the growth of breast cancer cells and kill cancer cells by increasing caspase-1, activating GSDMD, promoting the secretion of IL-1β, translocating HMGB1 towards the cytoplasm, and forming membrane pore." (PMID 33665167, 2020). "Huaier extract, a type of fungus from Trametes robiniophila, has shown its anti-cancer ability in non-small-cell lung cancer through caspase-1/GSDMD-dependent pyroptosis in vitro and in vivo." (PMID 33665167, 2020). "GSDMD exerts an essential but distinct role in different cancers, and it exhibits anti-cancer effects." (PMID 33665167, 2020). "Some studies have demonstrated that GSDMD is required for the activation of effector T-cell responses in cancer cells." (PMID 32149134, 2020). "Metformin is a common hypoglycemic agent, and it has been found to induce GSDMD-mediated pyroptosis in esophageal squamous cell carcinoma, a kind of chemo-refractory cancer, in vivo and in vitro." (PMID 33665167, 2020). "Another member of the gasdermin protein family, GSDMD, plays multifaceted roles in cancer pathogenesis." (PMID 31492049, 2019). "Moreover, aurigene 1 or AUPM 170 23 an oxadiazole-containing anti-neoplastic agent is employed in lung carcinoma and prompts pyroptosis in cancer cells through the activation of caspase-1 and GSDMD." (PMID 39316325, 2025). "Expression landscape and prognostic value of GSDMD across human cancers." (PMID 40491921, 2025). "In various types of cancer, GSDMD expression was positively correlated with active CD8+ T cells." (PMID 40759573, 2025). "In a variety of tumors (such as lung cancer and breast cancer), not only cancer cells themselves will produce EETs, but tumor related macrophages may also release EETs through mechanisms similar to GSDMD or other ways to promote cancer progression." (PMID 41459510, 2025). "The inhibition or activation of GSDMD can be applied to different disease treatment strategies, such as cancer immunotherapy that increases GSDMD expression and activates it, and anti‐inflammatory therapy that suppresses GSDMD expression to inhibit inflammatory cell death." (PMID 40273335, 2025). "Our findings suggest that GSDMD holds promise as a predictive biomarker for cancer immunotherapy." (PMID 40491921, 2025). "As several pharmacological modulators of GSDMD are available, this may lead to novel strategies for combination therapy in cancer." (PMID 39224600, 2024). "We then correlated GSDMD expression with survival in cancer patients." (PMID 39224600, 2024). "NLRP3/caspase-1/GSDMD-mediated pyroptosis is emerging as a promising therapeutic target in cancer treatment, thereby leading to the search for effective drugs and biomarkers for cancer treatment." (PMID 38265972, 2024). "In this work, we explored how GSDMD influenced cancer growth and immune infiltration." (PMID 39224600, 2024). "We detected the expression of GSDMD in several HCC cancer cells and found that GSDMD was expressed." (PMID 38178583, 2024). "Studies of inflammasome receptors and GSDMD have shed light on their roles in cancers." (PMID 38898209, 2024). "We employed two mouse models of CRC to interrogate the involvement of GSDMD in cancer." (PMID 38898209, 2024). "Similarly, lnc00958 was shown to promote cancer cell survival by downregulating miR-4306 levels to activate the absence in melanoma 2/Gasdermin D(GSDMD)-mediated pyroptosis pathway." (PMID 38799506, 2024).
cancer (continued). "The role of GSDMD and other members of the gasdermin family in cancer is less clear." (PMID 39224600, 2024). "Consequently, targeted strategies that activate GSDM, particularly GSDMD, are now being explored for cancer treatment." (PMID 39587093, 2024). "There is mounting evidence supporting the potential involvement of GSDMD in diverse cancers." (PMID 38584157, 2024). "Pyroptosis-regulating agents may also augment cancer immunotherapy by promoting the expression of gasdermin-D (GSDMD)." (PMID 39398428, 2024). "Our findings suggest that the role of GSDMD in cancer is strongly context-dependent." (PMID 39224600, 2024). "However, the available literature data suggest that gasdermin D (GSDM D) has an influence in the pathogenesis of cancers." (PMID 39766111, 2024). "GSDMD has also been identified as having cancer-promoting properties." (PMID 38304430, 2024). "GSDMD-mediated pyroptosis is involved in cancer cell death during chemotherapy and radiotherapy; however, secreted IL-1β may recruit immunosuppressive cell subsets and initiate inflammation-related side effects." (PMID 36932407, 2023). "It was manifested that GSDMD was crucial for an optimal CD8 + T cells response to cancer cells and the upregulation of gasdermin protein could also encourage the infiltration of M1 macrophages and CD8 + T cells." (PMID 37863886, 2023). "Moreover, after IL-17A treatment of these cancer cells, N-terminal GSDMD protein levels were increased." (PMID 37211606, 2023). "The interplay between GSDMD and these alternative cell death pathways may vary across different cancers, contributing to the observed heterogeneity." (PMID 38002346, 2023). "This analysis highlights the potential of GSDMD as a prognostic marker in various cancers." (PMID 38002346, 2023). "Research has revealed that GSDMD play a dual role in cancer." (PMID 38066523, 2023). "We further found that high expressions of GSDMD and GZMB displayed favorable prognosis in OC from six cohorts (P = 0.034 and P = 2.08E-5, respectively), GSDMD and GZMB were significantly associated with the expression of immune checkpoint molecules with pan-cancer analysis." (PMID 36707884, 2023). "Despite extensive research, the specific roles and mechanisms of GSDMD in cancer remain elusive." (PMID 38066523, 2023). "This could involve investigating the interaction between GSDMD and other molecules or pathways known to be involved in cancer development and progression." (PMID 38002346, 2023). "Additionally, a comprehensive analysis of GSDMD expression patterns and their correlation with clinical parameters in different cancer types would provide valuable insights into its prognostic significance." (PMID 38002346, 2023). "However, further in vivo or clinical verification studies are needed to fully understand the process of how pyroptosis and GSDMD affect cancer." (PMID 38002346, 2023). "GSDMD is silenced in GC compared to adjacent normal tissues and decreased expression could trigger proliferation of cancer cells." (PMID 37125240, 2023). "In different cancers, GSDMD plays different roles in the occurrence and development of tumors." (PMID 37483501, 2023). "GSDMC and GSDMD were found to be significantly upregulated in almost all cancer types." (PMID 35922531, 2022). "The pan-cancer analysis suggests that GSDMD plays a potential role in immunotherapy." (PMID 35784306, 2022). "Therefore, we performed the perturbation expression of pyroptosis regulators across another nearly 10,000 samples, representing 33 cancer types, and observed CASP3, CASP4, CASP8, and GSDMD were highly expressed in cancer cells." (PMID 35620284, 2022). "In pan-cancer, GSDMD had the relatively highest expression level while GSDMC had the lowest." (PMID 35164740, 2022). "Even the subcellular localization of GSDMD affects cancer progression and immune response." (PMID 36091247, 2022).
cancer (continued). "In 16 types of cancer, the correlation between GSDMD-enh3 and GSDMD expression was greater than that between CNV and GSDMD expression, suggesting that the alteration of the GSDMD gene expression is mainly caused by the activity change in the GSDMD-enh3." (PMID 35008400, 2022). "Subsequently, the caspase-1/GSDMD pathway is activated to induce cancer cell pyroptosis." (PMID 36091247, 2022). "Particularly, we revealed that GSDMD displayed the highest expression in 33 cancer types." (PMID 35620284, 2022). "Therefore, the idea of targeting GSDMD to induce cancer cell pyroptosis requires more careful selection and more in-depth exploration." (PMID 36091247, 2022). "In addition, exogenous overexpression of GSDMD by lentiviral transduction in K562 cells increased the anti-cancer activity of curcumin, and inhibiting the expression of GSDMD by shRNA enhanced U937 cells to resist curcumin." (PMID 35435150, 2022). "In different cancers, GSDMD and GSDME have different expression levels and functions." (PMID 36091247, 2022). "Owing to the important role of GSDMD/GSDME in the regulation of both pyroptosis and sensitivity to cancer therapy, a new role for pyroptosis may be implicated in the future." (PMID 36589680, 2022). "However, a previous study and our analysis revealed that the expression of one of the most important members of the gasdermin family, GSDMD, is significantly elevated in different types of cancers." (PMID 35289335, 2022). "Overexpressions of GSDMC and GSDMD have been observed in various types of cancer." (PMID 34858408, 2021). "While GSDMD-mediated pyroptosis was usually reported in immune cells upon inflammatory stimulations 17, 34, 35, and only a few studies reported that it occurred in the chemotherapeutic agent-treated cancer cells." (PMID 34326697, 2021). "We confirmed co-expression of NEK7 and GSDMD in cancer cells of PDAC tissues." (PMID 34295827, 2021). "However, a significantly upregulated GSDMD was observed in various types of cancer, such as cervical cancer, liver cancer, ovarian cancer, and pancreatic cancer." (PMID 34858408, 2021). "Considerable efforts should be dedicated to uncovering the detail function of GSDMD in cancer." (PMID 33634141, 2021). "We first screened several cancer cell lines for the expression of GSDMD and GSDME." (PMID 32332857, 2020). "Collectively, the expression of NLRP3, caspase-1, GSDMD, and IL-1β protein was higher in cancer and atypical hyperplasia tissues than in benign endometrial tissues, significantly difference were observed in key pyroptotic protein caspase-1 and GSDMD (P < 0.05)." (PMID 31924176, 2020). "GSDMD plays an important role in the regulation of pyroptosis and sensitivity to cancer therapy." (PMID 32958051, 2020). "GSDMD shows pro-tumorigenic or anti-tumorigenic abilities in different forms of cancer." (PMID 31492049, 2019). "Thus, it is critical to determine the molecular mechanisms contributing to the distinct impacts of GSDMD on cancer progression." (PMID 31492049, 2019). "A recent paper identified a small-molecule agonist of GSDMD and showed that it could induce protective antitumour immunity in various cancer models by inducing pyroptosis in a small fraction of cancer cells, without causing apparent systemic toxicity." (PMID 41315764, 2026). "However, a major challenge remains: how to effectively activate endogenous GSDMD in cancer cells." (PMID 39587093, 2024). "Pyroptosis is inflammatory programmed necrosis characterized by swelling and rupture of cells, induced by the overexpression of the protein gasdermin (GSDMD) in the cellular membrane, suggesting direct delivery of GSDMD to cancer cells could be an effective cancer treatment." (PMID 38505610, 2024). "However, whether GSDMD also plays a role in sporadic cancer development, especially that in the gut epithelium, remains unknown." (PMID 38898209, 2024). "Moreover, GSDMD localization of serves as a prognostic marker for malignant tumors." (PMID 38066523, 2023).
cancer (continued). "Therefore, in contrast to GSDMD, which supports inflammation and inflammatory diseases, cancer treatment strategies aiming for the activation of GSDMs might be promising." (PMID 37771587, 2023). "In addition to its impact on cancer cells, GSDMD also affects immune cells." (PMID 38066523, 2023). "Triggered by a hypoxic microenvironment, highly expressed ERRα could bind to the promoter of NLRP3 and inhibit caspase-1/GSDMD signaling, which reduced inflammasome activation and increased pyroptosis resistance, thereby resulting in the resistance of cancer cells to cisplatin." (PMID 37864196, 2023). "Moreover, GSDMD, a member of the gasdermin family, was differentially expressed in the vast majority of cancer and could be used as a prognostic marker in ACC." (PMID 36911522, 2023). "GSDMD may be crucial for establishing an inflammatory microenvironment around cancer cells." (PMID 33634141, 2021). "Notably, GSDMD, an important mediator of pyroptosis, was seldom investigated in cancer." (PMID 34830775, 2021). "And, strictly speaking, as knockdown of MEG3 only partly abolished the activation of DDP-induced NLRP3/caspase-1/GSDMD pathway and anti-cancer functions in MDA-MB-231 cells, MEG3 may partially mediated the pyroptotic signaling upon DDP treatment in this type of TNBC cell line." (PMID 34326697, 2021). "However, GSDMD functions oppositely in other types of cancer." (PMID 31492049, 2019). "It is intriguing whether GSDMD-induced pyroptosis occurs in cancer cells." (PMID 31492049, 2019). "GSDMD expression exhibited a strong correlation with monocytes, resting mast cells, resting dendritic cells, and activated CD4 memory T cells in most cancers." (PMID 40491921, 2025). "Although recent research has established that gasdermin D (GSDMD), a factor that drives pyroptosis, is essential for cell death and inflammation, its involvement in cancer metastasis has yet to be elucidated." (PMID 40324993, 2025). "Across cancers, NLRP3, GSDMD, and SIRT1 emerge as the most recurrent ncRNA-regulated pyroptosis components." (PMID 41291696, 2025). "Activated caspase-1 then cleaved Gasdermin D (GSDMD), releasing its N-terminal pore-forming domain, which inserted into the plasma membrane and ultimately induced pyroptosis in cancer cells." (PMID 41144097, 2025). "Additionally, we speculate that gasdermin D as a protein modulating the immune system response may contribute to the development of a chronic inflammatory state, which is one of the factors that may contribute to the development of cancer." (PMID 39766111, 2024). "Limited data from public databases indicate a positive correlation between CAF infiltration and the expression of GSDMD and GSDME in cancer cells, suggesting the potential for CAF-induced pyroptosis in cancer cells." (PMID 38649701, 2024). "Therefore, targeting GSDMD may be a novel approach to the treatment of cancer." (PMID 37371484, 2023). "Ophiopogonin B, derived from Dioscorea bulbifera L., can induce caspase-1/GSDMD-dependent pyroptosis in lung cancer cells, especially exhibiting a more significant suppression of growth in DDP-resistant cancer cells." (PMID 38239395, 2023). "While our study focused on elucidating the role of GSDMD in cell pyroptosis and its potential as an early biomarker for inflammatory diseases, we acknowledge that the specific mechanisms underlying the diverse disease outcomes in different cancers were not extensively discussed." (PMID 38002346, 2023). "In different cancers, GSDME has different expression levels and functions, and even the subcellular localization of GSDMD affects cancer progression and immune response." (PMID 37415742, 2023). "Significantly upregulated PRGs included PYCARD in 12 cancers; GSDMB in 10 cancers; IL18 in 9 cancers; GSDMD, CASP8, GZMB, and GPX4 in 8 cancers; AIM2 and CASP6 in 7 cancers; GZMA in 6 cancers; GSDME, CASP4 and DHX9 in 5 cancers; GSDMA and GSDMC in 4 cancers." (PMID 36605187, 2022).